MEGF8 (multiple EGF like domains 8)
Description:
Acts as a negative regulator of hedgehog signaling.
Synonyms: C19orf49; EGFL4; SBP1; FLJ22365; CRPT2
Tractability: Antibody: UniProt predicts a signal peptide or a membrane-spanning region. PROTAC: its protein half-life has been measured.
Gene: Protein-coding gene on chromosome 19 (42,325,609 to 42,378,769, forward strand). Ensembl gene ENSG00000105429.
Subcellular location: Membrane
Gene Ontology:
Molecular function: protein binding; calcium ion binding
Biological process: cell migration involved in gastrulation; craniofacial suture morphogenesis; determination of heart left/right asymmetry; epiboly involved in gastrulation with mouth forming second; left/right pattern formation; limb morphogenesis; BMP signaling pathway; determination of digestive tract left/right asymmetry; embryonic heart tube left/right pattern formation; embryonic heart tube morphogenesis; embryonic limb morphogenesis; embryonic skeletal system morphogenesis; fasciculation of sensory neuron axon; negative regulation of smoothened signaling pathway; positive regulation of axon extension involved in axon guidance; regulation of gene expression; signal transduction; embryonic morphogenesis; morphogenesis of an epithelium; skeletal system morphogenesis
Cellular component: extracellular exosome; nucleus; membrane; ubiquitin ligase complex
Genetic constraint (gnomAD): Loss-of-function variants: 151 observed, 248.44 expected, observed/expected ratio (o/e) 0.61, 90% interval 0.53 to 0.7. The upper end of that interval is the gene's LOEUF score, 0.7, which puts it in group 2 of 6, group 1 being the genes least tolerant of losing a copy. Missense variants: 3,320 observed, 3,682.1 expected, observed/expected ratio (o/e) 0.9, 90% interval 0.88 to 0.93. Synonymous variants: 1,605 observed, 1,543.7 expected, observed/expected ratio (o/e) 1.04, 90% interval 1 to 1.08.
Gene-disease validity (ClinGen):
ClinGen rates the evidence that MEGF8 causes each of these diseases.
MEGF8-related Carpenter syndrome (autosomal recessive): Moderate.
Homologues: Orthologues: chimpanzee MEGF8 (99% identical), macaque MEGF8 (96% identical), guinea pig MEGF8 (94% identical), mouse Megf8 (94% identical), rat Megf8 (94% identical), tropical clawed frog megf8 (58% identical), zebrafish megf8 (56% identical), dog MEGF8 (15% identical). Paralogues in human: ATRN (13% identical), ATRNL1 (13% identical), LAMA5 (10% identical), LAMA3 (9% identical), LAMB2 (8% identical), LAMA2 (8% identical), LAMA1 (8% identical), LAMB1 (8% identical), LAMB4 (8% identical), HSPG2 (7% identical), LAMC3 (7% identical), LAMC1 (7% identical), and 15 more.
Diseases named in the same sentence as MEGF8 in open-access papers:
MEGF8 is named in the same sentence as 28 diseases in open-access papers, as found by Europe PMC text mining. Sharing a sentence is not in itself a finding about the gene and the disease. The quoted sentences say what the papers report.
Carpenter syndrome (12 papers, 2013 to 2024). An extremely rare autosomal recessive syndrome characterized by premature closure of cranial sutures leading to cone-shaped head, fusion of the digits, and the presence of more digits than normal. "Targeted next generation sequencing with 300 gene capture and analysis of 50 genes associated with craniosynostosis identified two variants in MEGF8, consistent with the characteristic phenotype of Carpenter syndrome." (PMID 38760421, 2024). "We identified MEGF8, associated with carpenter syndrome, to be downregulated in the IUO offspring while LAMTOR4, associated with the regulator complex involved in lysosomal signaling and trafficking, was found to be upregulated in the PNO groups, respectively." (PMID 35681434, 2022). "Of these, MEGF8, associated with carpenter’s syndrome, was downregulated in the IUO SVs, and LAMTOR4, a regulator of microglial lysosomes, was upregulated in the PNO SVs." (PMID 35681434, 2022). "Defects in the gene that encodes MEGF8 result in carpenter syndrome, which is defined as congenital malformation described by craniosynostosis and polysyndactyly." (PMID 35681434, 2022). "In each case the second variant, a heterozygous missense, was not specifically flagged, even though the patient had a very characteristic phenotype (MEGF8: Carpenter syndrome; MMP21: heterotaxy) associated with a limited number of known disease-causing genes." (PMID 34429528, 2021). "Mutations in the human MSX2, TWIST1, TCF12, SKI, and MEGF8 genes are associated with Boston-type craniosynostosis, Saethre–Chotzen syndrome, coronal craniosynostosis, Shprintzen–Goldberg syndrome, and Carpenter syndrome, respectively." (PMID 34490030, 2021). "Mutations of the gene MEGF8 cause Carpenter syndrome in humans, and the mouse orthologue has been functionally associated with Nodal and Bmp4 signalling." (PMID 29884872, 2018). "Mutations in MEGF8 cause a subtype of Carpenter's syndrome associated with heterotaxy, congenital cardiac defects, pre-axial polydactyly, and skeletal and craniofacial defects." (PMID 29290584, 2018). "Homozygous recessive MEGF8 mutations have been described in five patients with the Carpenter syndrome subtype associated with defective lateralization." (PMID 28787007, 2017). "Mutations in multiple epidermal growth factor-like domain 8 (MEGF8), a multidomain transmembrane protein encoded by a gene conserved across species, cause Carpenter’s syndrome, which is associated with learning disabilities, mental health issues, and left–right patterning abnormalities." (PMID 38201267, 2023). "Interestingly, mutations in Megf8 were recently identified in a small subset of children with Carpenter syndrome, which is an autosomal-recessive multiple-congenital-malformation disorder." (PMID 24052814, 2013). "On the other hand, variants of MEGF8 (OMIM-G 604267), a gene related to TGA in Carpenter syndrome, were found in two patients." (PMID 36140829, 2022).
cryptorchidism (3 papers, 2018 to 2024). The failure of one or both testes of a male fetus to descend from the abdomen into the scrotum during the late part of pregnancy. "Combined with previously reported males with MEGF8-associated CRPT2, all males with MEGF8-associated CRPTS have demonstrated cryptorchidism, which is also common but not universally reported in RAB23-associated CRPT1 (MEGF8: 9/9 males; RAB23 14/23 males; Fisher’s exact P = 0.035)." (PMID 38760421, 2024).
craniosynostosis (2 papers, 2022 to 2024). Craniosynostosis is defined as the premature fusion of one or more cranial sutures leading to secondary distortion of skull shape resulting in skull deformities with a variable presentation. "Considering all patients with MEGF8-associated CRPT2 to date, six out of fifteen cases have had involvement of a single midline suture, comprising five with metopic and one with sagittal craniosynostosis, and only four individuals had multiple suture craniosynostosis." (PMID 38760421, 2024). "Craniosynostosis is a nearly universal feature in cases of both RAB23- and MEGF8-associated CRPTS." (PMID 38760421, 2024).
Intellectual disability (2 papers, 2017 to 2020). "Mild to moderate intellectual disability have been observed in some Carpenter subjects (OMIM:201000) although these symptoms have not been reported in the five cases with the subtype due to MEGF8 mutations." (PMID 28787007, 2017).
aortic root dilatation (1 paper, 2012). "On gene expression level, decreased expression of MEGF8 gene was found in MFS patients with aortic root dilatation." (PMID 22479353, 2012). "It revealed one significantly down-regulated gene in patients with aortic root dilatation: MEGF8 (Multiple Epidermal Growth Factor-like-domains 8) (FDR = 0%, FC = 0.62)." (PMID 22479353, 2012).
Saethre-Chotzen syndrome (1 paper, 2021). Saethre-Chotzen syndrome (SCS) is an inherited craniosynostosis syndrome characterized by unilateral or bilateral coronal synostosis, facial asymmetry, ptosis, strabismus and small ears with prominent crus, among other less common manifestations. "Genes associated with the other syndromes (e.g., Carpenter [RAB23 gene, MEGF8 gene], Apert [FGFR2 gene], Crouzon [FGFR2 gene], Pfeiffer [FGFR2 gene, FGFR1 gene], and Saethre-Chotzen syndromes [TWIST1 gene]) were analyzed by WES analysis and none of these mutations were found on the patients." (PMID 34348791, 2021).
schizophrenia (1 paper, 2017). A major psychotic disorder characterized by abnormalities in the perception or expression of reality. "A MEGF8 mutation was found in the patient with the 3q29 deletion (patient 2), a CNV highly penetrant in schizophrenia, but also associated with a range of other neurodevelopmental phenotypes." (PMID 28787007, 2017).
heart disease (1 paper, 2024). "Congenital heart disease is present in 6/8 cases reported here, 4/7 previously reported cases of MEGF8-associated CRPTS and 10/39 previously reported cases of RAB23-associated CRPTS." (PMID 38760421, 2024).
MEGF8 also shares sentences with these, for which no sentence is quoted: Polysyndactyly (3 papers); congenital heart disease (2); Acrocephaly (1); Autoimmunity (1); brain injury (1); cancer (1); cannabis dependence (1); Cognitive impairment (1); developmental delay (1); endolymphatic hydrops (1); epilepsy (1); esophageal cancer (1); Fallot tetralogy (1); neuropathy (1); Obesity (1); Parkinsonism (1); pulmonary stenosis (1); stenosis (1); Talipes equinovarus (1); Umbilical hernia (1).